ACSM2A (acyl-CoA synthetase medium chain family member 2A)
Description:
Catalyzes the activation of fatty acids by CoA to produce an acyl-CoA, the first step in fatty acid metabolism (By similarity). Capable of activating medium-chain fatty acids (e.g. butyric (C4) to decanoic (C10) acids), and certain carboxylate-containing xenobiotics, e.g. benzoate (By similarity).
Synonyms: ACSM2; A-923A4.1; MGC150530
Tractability: Small molecule: a structure with a bound ligand is known; it has a high-quality binding pocket. PROTAC: its protein half-life has been measured.
Gene: Protein-coding gene on chromosome 16 (20,444,012 to 20,487,669, forward strand). Ensembl gene ENSG00000183747.
Subcellular location: Mitochondrion
Pathways (Reactome):
Drug ADME: Aspirin ADME
Metabolism: Conjugation of salicylate with glycine
Gene Ontology:
Molecular function: medium-chain fatty acid-CoA ligase activity; benzoate-CoA ligase activity; decanoate-CoA ligase activity; fatty acid ligase activity; fatty-acyl-CoA synthase activity; CoA-ligase activity; short-chain fatty acid-CoA ligase activity
Biological process: medium-chain fatty-acyl-CoA metabolic process; acyl-CoA metabolic process; fatty acid biosynthetic process; glucose homeostasis; triglyceride homeostasis
Cellular component: mitochondrion; mitochondrial matrix
Genetic constraint (gnomAD): Loss-of-function variants: 72 observed, 71.07 expected, observed/expected ratio (o/e) 1.01, 90% interval 0.84 to 1.23. The upper end of that interval is the gene's LOEUF score, 1.23, which puts it in group 5 of 6, group 1 being the genes least tolerant of losing a copy. Missense variants: 680 observed, 677.93 expected, observed/expected ratio (o/e) 1, 90% interval 0.94 to 1.07. Synonymous variants: 245 observed, 244.59 expected, observed/expected ratio (o/e) 1, 90% interval 0.9 to 1.11.
Homologues: Orthologues: chimpanzee ACSM2A (93% identical), rat Acsm2 (77% identical), mouse Acsm2 (76% identical), tropical clawed frog acss2.2 (26% identical), zebrafish acss2l (24% identical), Caenorhabditis elegans acs-2 (17% identical), Caenorhabditis elegans acs-1 (16% identical). Paralogues in human: ACSM2B (97% identical), ACSM4 (57% identical), ACSM1 (55% identical), ACSM3 (54% identical), ACSM5 (54% identical), ACSM6 (34% identical), ACSS2 (27% identical), ACSS1 (27% identical), ACSS3 (25% identical), AACS (21% identical), ACSF2 (20% identical), ACSF3 (18% identical), and 1 more.
Diseases named in the same sentence as ACSM2A in open-access papers:
ACSM2A is named in the same sentence as 6 diseases in open-access papers, as found by Europe PMC text mining. Sharing a sentence is not in itself a finding about the gene and the disease. The quoted sentences say what the papers report.
chronic kidney disease (1 paper, 2022). Impairment of the renal function secondary to chronic kidney damage persisting for three or more months. "A genome-wide association study on chronic kidney disease also identified the relationship between ACSM2A and eGFR, showing its potential of being a kidney injury biomarker." (PMID 35860471, 2022).
hypertriglyceridemia (1 paper, 2021). A laboratory test result indicating elevated triglyceride concentration in the blood. "PD strain displays significant downregulation of three acyl-CoA-generating enzymes (ACSM3, ACSM2A, ACSL5), which can contribute to the lower ability to utilize fatty acids and hypertriglyceridemia in this strain." (PMID 33923085, 2021).
tumor (1 paper, 2025). "ROC and KM curves further underscored the significance of ACSM2A in tumor diagnosis and prognosis." (PMID 39744494, 2025).
ACSM2A also shares sentences with these, for which no sentence is quoted: cancer (1 paper); Hyperammonemia (1); liver cancer (1).